PARP1 (poly(ADP-ribose) polymerase 1)
Diseases named in the same sentence as PARP1 in open-access papers (continued):
Sharing a sentence is not in itself a finding about the gene and the disease.
breast cancer (continued). "In addition, veriparib (veliparib), a novel potent PARP-1 and PARP-2 inhibitor, had a 51% partial remission rate in the treatment group in a clinical phase II trial of breast cancer treatment, which was significantly higher than the standard chemotherapy group (26%)." (PMID 34198652, 2021). "However, the mechanism of the effect of PARP1, XRCC4 and ERCC1 on the metastasis of breast cancer remains unclear, which needs further study (Fig. S1A1)." (PMID 33184404, 2020). "By increasing caspase-3, caspase-9, and poly (ADP-ribose) polymerase 1 (PARP-1), EGCG downregulated the expression of miR-25, which reduced the cell growth and proliferation rate, resulting in G2/M phase arrest and, ultimately, increased cell apoptosis in several breast cancer cell lines." (PMID 33113766, 2020). "Although PARP1 inhibitor therapy has predominantly targeted Breast Cancer (BRCA)-mutated cancers, there is growing evidence that PARP1 inhibitor treatment for non-BRCA-mutant tumors might be beneficial for CIN+ tumors." (PMID 33003585, 2020). "Thus, it might be an effective combinatorial treatment with PARP1 and CCR2 inhibitors to achieve better outcomes where CCL2 levels are determined to be high, particularly in breast cancer, as well as other solid tumors." (PMID 32455851, 2020). "We compared the expression in cell lines from PARP1 inhibitor treatable cancers (triple negative breast and high grade serous cancers) with cell lines from PARP1 inhibitor not-treatable cancers (hormone receptors-breast cancer and ovarian clear cell cancer)." (PMID 31105872, 2019). "PARP1 activity has been shown to be an important regulator of ERα function; however, whether ERα PARylation is involved in breast cancer and furthermore tamoxifen resistance has not been examined." (PMID 30621214, 2019). "The fact that at least some of them were previously confirmed to be enriched in BRG1–EP300 functional complexes prompted us to check if EP300 interacted with PARP1 and if any of BRG1–EP300 components could undergo ADP-ribosylation in proliferating breast cancer cells." (PMID 31614656, 2019). "In general, downregulation of PARP1 could modulate many factors in the cell life cycle and cell death to suppress proliferation of carcinomas, which has been demonstrated in PARP−/− mice models and human breast cancer cells, and so on." (PMID 28991194, 2017). "Despite the activation of initiator caspase 8 and 9, in our experimental conditions the canonical apoptosis pathway was not reaching the end, as both DNA ladder and PARP-1 proteolysis were absent; the absence of PARP-1 proteolysis was recently described also in HMA-treated breast cancer cells." (PMID 27816051, 2016). "Treatment of these breast cancer cells with 2,3,7,8-tetrachlorodibenzo-p-dioxin (TCDD), which is itself an estrogenic toxicant, altered the expression of enzymes responsible for the bio-activation of estrogen leading to DNA damage, PARP1 activation and DNA repair." (PMID 19961617, 2009). "In model mice with a single deficiency in T cell PARP1 or PARP2, there is no change in the number of T cells in peripheral lymphoid tissues, but the double deficiency of PARP1 and PARP2 leads to a reduction in peripheral CD4+ CD8+ T cells in breast cancer model mice." (PMID 38111536, 2023).
breast cancer (continued). "Based on the enhanced sensitivity of tumor cells with inactivated tumor suppressor genes BRCA 1 and 2 towards PARP-1 inhibition, the PARP inhibitors olaparib, rucaparib, and niraparib could recently receive FDA approval for the treatment of BRCA-mutant ovarian and refractory breast cancers." (PMID 29794999, 2018). "Furthermore, many PARP1 inhibitors were demonstrated to be not only effective against familial DNA repair defective carcinomas, but also against HR-proficient cancers, like HR-proficient HER2+ breast carcinoma and Ewing’s sarcoma, in pre-clinical or clinical studies." (PMID 28991194, 2017). "Thus, PARP1 overexpression may impede drug effect only above a certain threshold and this mechanism of resistance may only apply to some but not all breast cancers." (PMID 25144364, 2014). "However, our lab has demonstrated that PARP-1 inhibition also kills HER2+ breast cancer cells despite proficient HR repair, indicating PARP-1 may be an effective treatment for non-familial, sporadic cancers as well as familial cancers." (PMID 24202328, 2013). "However, in view of findings indicating that activated PARP-1 highly augments the activity of ERK in the nucleus even in the absence of DNA damage, a different therapeutic potential of PARP inhibitors is examined in breast cancer cells lacking BRCA mutations." (PMID 19891779, 2009). "A study reported that Olaparib induced breast cancer-mediated bone metastasis via PARP-2, but not PARP-1, in the myeloid lineage, not in the tumor cells." (PMID 38260135, 2023). "This PARP-1-dependent AMPK nuclear export for autophagy induction is not widely reported, to date has only been reported in breast cancer cells and fibroblasts upon starvation." (PMID 37936170, 2023). "Proliferation, migration, colony formation, cell cycle, and poly [ADP-ribose] polymerase 1 (PARP-1) and vascular endothelial growth factor (VEGF) detection assays were performed with MCF7 breast cancer cells and MCF10A non-tumor cells." (PMID 36499129, 2022). "Here we show that olaparib increases breast cancer bone metastasis through PARP2, but not PARP1, specifically in the myeloid lineage, but not in the cancer cells." (PMID 32221289, 2020). "Subsequently, other studies clarified that PARP1 is more active in cancer cells that, due to the lack of function of ATM, accumulated DNA damage (most represented and studied in prostate cancer, breast cancer, mantle cell lymphoma)." (PMID 28055979, 2017). "A new study shows that Olaparib might increase breast cancer bone metastasis through PARP2 (poly ADP-ribose polymerase), but not PARP1, particularly in myeloid lineage and not in cancer cells." (PMID 32443642, 2020). "This may be attributed to the fact that PARP1 has predominantly been reported to play a key role in the DNA damage response and the repair of single-stranded breaks (SSBs) through the base excision repair (BER) in breast cancer rather than as a critical gene in the parthanatos." (PMID 40564403, 2025).
ovarian carcinoma (295 papers, 2008 to 2026). A malignant neoplasm originating from the surface ovarian epithelium. "Specifically, the p.R591 C, a clinically relevant PARP mutation found in an olaparib-resistant ovarian cancer patients promotes dissociation of PARP1 from the DNA damage site showing inefficient PARP trapping resulting in PARP resistance." (PMID 40521389, 2025). "Defects in the DNA repair pathways, such as mutations in BRCA1 and BRCA2, can enhance the PARP1 activity in breast and ovarian cancers." (PMID 41219748, 2025). "The most noteworthy example is the synthetic lethal interaction between BRAC1/2 mutations and inhibition of PARP1 protein expression by PARP1 inhibitors in breast and ovarian cancers." (PMID 40624356, 2025). "An ovarian cancer patient with de novo resistance to olaparib was found to harbour a p.R591C mutation affecting the WGR domain of PARP1." (PMID 39135999, 2024). "Actually, de novo PARPi resistance caused by PARP1 mutation had been identified in ovarian cancer patient." (PMID 39318358, 2024). "The presence of BRCA1/2 mutations in the ctDNA of ovarian cancer patients was observed, and these patients showed a positive response to targeted therapy with PARP1 inhibitors." (PMID 39492906, 2024). "The high PARP1-inhibitory activity of RSV makes it a promising candidate for the therapy of breast and ovarian cancers having the susceptibility gene mutation (BRCAm), where the use of synthetic PARP1 inhibitors is currently recommended." (PMID 39595575, 2024). "PARP1 inhibitors, in particular Olaparib, are currently used in the clinic to treat breast and ovarian cancer patients carrying germline mutations in BRCA1/235." (PMID 36707518, 2023). "Recently approved PARP1 inhibitors for BRCA1/2-linked ovarian cancer (OC) produced major response rates for patients with BRCA1/2-linked advanced OCs." (PMID 37095508, 2023). "PARP1 p.R591C mutation (c.1771C>T) was detected in ovarian cancer patient who showed resistant to olaparib." (PMID 35785170, 2022). "In ovarian cancer, some clinically relevant trials have reported that high expression of PARP1 is associated with drug resistance and poor prognosis." (PMID 35875162, 2022). "Mutations in PARP1 correlate with protein instability and PARPi resistance has been observed in different human tumors, including ovarian cancer." (PMID 35406579, 2022). "In BRCA germline deficient or platinum sensitive ovarian cancers, PARP1 inhibitor (Niraparib, Rucaparib, Olaparib, Talazoparib) maintenance therapy improves progression-free survival." (PMID 35853939, 2022). "Targeting PARP1 [Poly(ADP-Ribose) Polymerase 1] for synthetic lethality is a new strategy for BRCA germ-line mutated or platinum sensitive ovarian cancers." (PMID 33674744, 2021). "We found that PARP1 rs8679 and hOGG1 rs293795 polymorphisms were associated with a decreased risk of ovarian cancer under dominant model (adjusted OR=0.39, 95% CI=0.17-0.90, P=0.026; and adjusted OR=0.36, 95% CI=0.13-0.99, P=0.049, respectively)." (PMID 33391423, 2021). "For example, the PARP1 gene has been proven to be an essential gene specific to mutated BRCA (i.e., synthetically lethal to mutated BRCA), and the use of the PARP1 inhibitor olaparib was approved for treating BRCA-mutated ovarian cancer." (PMID 34681774, 2021). "In vitro studies have implicated a role for PARP-1 induction of vascular endothelial growth factor (VEGF) angiogenesis in spread of epithelial ovarian cancer cells." (PMID 34070674, 2021). "PARPis resistance has been described in an ovarian cancer patient carrying a point mutation in PARP-1." (PMID 33167404, 2020). "KJ-28d inhibited PARP-1/2 activities and displayed significant antitumor activity in human ovarian cancer BRCA1-deficient (BRCA1 mutation at 5564G>A) SNU-251 cells." (PMID 31795418, 2019). "In parallel with these genetic studies, we identified a PARP1 p.R591C mutation (c.1771C>T) in an ovarian cancer patient who showed de novo resistance to olaparib." (PMID 29748565, 2018).
ovarian carcinoma (continued). "In the case of PARP-1 inhibitors, studies were historically focused on familial and sporadic breast and ovarian cancers with bi-allelic mutations in the HR repair genes BRCA1, BRCA2, or PALB2." (PMID 29998112, 2018). "The PARP1 inhibitor, olaparib, has been approved to treat breast and ovarian cancer patients who have germline mutations in BRCA1/2." (PMID 29783721, 2018). "Such an approach has been successfully exploited with the use of PARP inhibitors for the treatment of BRCA deficient ovarian cancer, wherein inhibition of PARP1 mediates mitotic catastrophe and apoptosis of BRCA deficient cells." (PMID 29348827, 2017). "Olaparib and niraparib are both orally active PARP1 inhibitors that are effective in the treatment of ovarian cancers with BRCA1 and BRCA2 mutations." (PMID 28756516, 2017). "Olaparib is the only PARP1/2 inhibitor approved for treatment of pretreated or platinum sensitive ovarian cancer associated with defective BRCA1/2 genes." (PMID 29262611, 2017). "Approximately 25% of patients with ovarian cancer harbor a pathogenic BRCA1/2 mutation that has been associated with favorable responses for targeted therapy with poly (ADP-ribose) polymerase 1 (PARP1) inhibitors compared to wild-type individuals." (PMID 29254167, 2017). "Olaparib is an oral PARP1 inhibitor that has been recently approved for the treatment of relapsed ovarian cancer that harbors BRCA1 or 2 mutations." (PMID 28756516, 2017). "For example, targeting the PARP-1 enzyme using Olaparib in ovarian cancer patients carrying a tumor BRCA1/2 mutation achieved milestone success in this area." (PMID 27438146, 2016). "Olaparib is a novel PARP inhibitor with increased specificity for PARP-1 and -224 that was approved for the treatment of ovarian cancer positive for BRCA1/2 mutations (FDA reference ID: 3675412) in 2014." (PMID 28004814, 2016). "The PARP-1 inhibitor olaparib is approved for use in BRCA-mutated ovarian cancers but BRCA2-reversion mutations lead to functional homologous recombination repair (HRR) and olaparib resistance." (PMID 26959114, 2016). "Here, we show that the hypomethylated ETS1 motif is a key regulatory element for the PARP1 gene in BRCA1-mutated ovarian cancer." (PMID 24448423, 2014). "The present study showed that BRCA-mutated ovarian cancer displayed a relatively hypomethylated PARP1 promoter, but significantly higher methylation as noted particularly around the ETS motif in normal ovarian tissue." (PMID 23442605, 2013). "Nanoparticle-mediated delivery of PARP1-specific siRNA inhibited growth of BRCA1-deficient mouse ovarian cancer allografts; this effect was at least in part attributed to apoptotic death of targeted cells." (PMID 21819606, 2011). "Several PARP-1 inhibitors are currently in phase I or II of clinical monotherapy trials in BRCA1/BRCA2-deficient breast or ovarian cancers." (PMID 19319136, 2009). "Consequently, miR-622-mediated HR restoration reduces sensitivity to PARP1 inhibitors in BRCA1-mutated ovarian cancer (OvCa) cells." (PMID 41008855, 2025). "Interestingly, in ovarian cancer patients, the PARP1 p.R591C mutation (c.1771C>T) showed de novo resistance to olaparib, showing clinical evidence of PARP mutations as another mechanism of PARPi resistance." (PMID 37190285, 2023). "In setting diagnostic goals, scientists have found a number of PARP-1 inhibitors, that can be used in many anti-cancer therapies, and are already applied in the treatment of gynecological cancers, such as endometrial, breast and ovarian cancer." (PMID 36831138, 2023). "Interestingly, ovarian cancer patients with the PARP1 p.R591C mutation (c.1771C>T) showed de novo resistance to olaparib, suggesting that this is partly validated in clinics as a mechanism of resistance to PARP inhibitors." (PMID 35955544, 2022).
ovarian carcinoma (continued). "Since Olaparib7 was approved as the first PARP-1 inhibitor to treat advanced ovarian cancer associated with defective BRCA mutations in 2014, several PARP inhibitors were approved subsequently, including Rucaparib8, Niraparib9, Talazoparib10, Fluzoparib11,12, and Pamiparib13,14." (PMID 35317687, 2022). "Deletion of PARP1 using CRISPR/Cas9 gene editing tools in two ovarian cancer cells (one with BRCA1 mutation and one with BRCA1 promoter methylation) shows >90% reduction of PARP1 expression in BRCA1 mutant and promoter methylated cells as measured by immunofluorescence and western blot analysis." (PMID 35785170, 2022). "However, more comprehensive studies with larger independent cohorts should be provided to verify the relationship between these significant genetic variations in PARP1 and hOGG1 gens and ovarian cancer risk." (PMID 33391423, 2021). "These included several proteins with well-known associations to PARP1 in ovarian cancer." (PMID 34686201, 2021). "The BRCA1/2 mutations could be detected in the ctDNA from ovarian cancer patients, which responded well to the targeted therapy of the PARP1 inhibitors." (PMID 33936202, 2021). "In conclusion, our study suggested that the PARP1 and hOGG1 polymorphisms might correlate to ovarian cancer susceptibility." (PMID 33391423, 2021). "Several studies have shown that loss-of-function mutation of canonical HR factors – such as breast cancer type 1 and 2 (BRCA1/2) susceptibility proteins that are commonly associated with breast and ovarian cancer – promotes PARP1 hyperactivation in fast replicating cancer cells." (PMID 32295316, 2020). "PARP-1 inhibitor Olaparib has been initially approved as monotherapy for the maintenance treatment of adult patients with platinum-sensitive relapsed BRCA-mutated (germline or somatic) high-grade ovarian cancer." (PMID 32903519, 2020). "Therefore, DNA repair proteins, XRCC1 and PARP1, have been associated with significantly aggressive clinical outcome of ovarian cancer patients and decreased cisplatin sensitivity in OC cells." (PMID 33076245, 2020). "High expression of PARP1 in ovarian cancer is associated with poor survival." (PMID 29684820, 2018). "This article reviews reported relationships between various miRNAs, such as miRNA-9, miRNA-146a, miRNA-182 miRNA-218, miRNA-638 and the response to cytostatic drugs, mainly to platins and PARP1 inhbitors, for the treatment of breast and ovarian cancer associated with BRCA1 mutations." (PMID 29021870, 2017). "Notably, the ETS1 motif was the critical site for PARP1 transcription only in BRCA1-mutated ovarian cancer cells (Fig. 1Bi-Biv)." (PMID 24448423, 2014). "Our previous results suggested that promoter hypomethylation, especially around the ETS1 and ETS2 motifs, may be involved in the up-regulation of PARP1 expression in BRCA1-mutated ovarian cancer." (PMID 24448423, 2014). "Thus, it is important for future studies to analyze DNA methylation patterns of the PARP1 promoter in the DNA methylation-associated inactivation of the BRCA1 gene in ovarian cancer." (PMID 23442605, 2013). "In contrast, the siRNA for PARP-1 could specifically prevent the growth of BRCA-deficient ovarian cancer cell-derived tumors in mice." (PMID 24294592, 2013). "Moreover, as activation of NF-κB has been linked to the resistance of ovarian cancer cells to PARP1 inhibitors, targeting this pathway could improve the outcome of the CDK12-PARP1 combination therapy." (PMID 37811895, 2023). "Likewise, it allows the identification of those patients who may be susceptible to a targeted treatment, such as PARP1 inhibitors, which currently have national approval for the treatment of recurrent ovarian cancer." (PMID 31545835, 2019).